ANXA7 (annexin A7)
Description:
Calcium/phospholipid-binding protein which promotes membrane fusion and is involved in exocytosis.
Synonyms: ANX7; SNX; SYNEXIN
Tractability: Antibody: its Gene Ontology location is reachable by antibodies, with medium confidence. PROTAC: ubiquitination databases record sites on it; its protein half-life has been measured.
Target class: Ion channel; Annexin; Other ion channel
Gene: Protein-coding gene on chromosome 10 (73,375,101 to 73,414,731, reverse strand). Ensembl gene ENSG00000138279.
Gene Ontology:
Molecular function: calcium-dependent protein binding; integrin binding; protein binding; RNA binding; calcium-dependent phospholipid binding; phosphatidylserine binding; calcium ion binding; GTPase-dependent fusogenic activity
Biological process: autophagy; epithelial cell differentiation; negative regulation of gene expression; membrane fusion; response to calcium ion; response to phorbol 13-acetate 12-myristate
Cellular component: chromaffin granule membrane; endoplasmic reticulum membrane; extracellular exosome; extracellular matrix; membrane; nucleus; plasma membrane; vesicle membrane; alveolar lamellar body; cytosol; nuclear envelope; vesicle
Genetic constraint (gnomAD): Loss-of-function variants: 37 observed, 46.12 expected, observed/expected ratio (o/e) 0.8, 90% interval 0.62 to 1.05. The upper end of that interval is the gene's LOEUF score, 1.05, which puts it in group 4 of 6, group 1 being the genes least tolerant of losing a copy. Missense variants: 462 observed, 513.53 expected, observed/expected ratio (o/e) 0.9, 90% interval 0.83 to 0.97. Synonymous variants: 169 observed, 171.63 expected, observed/expected ratio (o/e) 0.98, 90% interval 0.87 to 1.12.
Homologues: Orthologues: chimpanzee ANXA7 (99% identical), macaque ANXA7 (99% identical), pig ANXA7 (94% identical), dog ANXA7 (93% identical), rabbit ANXA7 (93% identical), mouse Anxa7 (92% identical), rat Anxa7 (92% identical), guinea pig ANXA7 (91% identical), tropical clawed frog anxa7 (72% identical), Drosophila melanogaster AnxB11 (40% identical), Drosophila melanogaster AnxB9 (36% identical). Paralogues in human: ANXA11 (52% identical), ANXA8 (35% identical), ANXA8L1 (35% identical), ANXA13 (33% identical), ANXA4 (33% identical), ANXA5 (33% identical), ANXA1 (32% identical), ANXA6 (32% identical), ANXA3 (31% identical), ANXA2 (30% identical), ANXA10 (26% identical), ANXA9 (23% identical).
Diseases named in the same sentence as ANXA7 in open-access papers:
ANXA7 is named in the same sentence as 64 diseases in open-access papers, as found by Europe PMC text mining. Sharing a sentence is not in itself a finding about the gene and the disease. The quoted sentences say what the papers report.
prostate carcinoma (18 papers, 2008 to 2024). A carcinoma that arises from epithelial cells of the prostate gland. "From the results of our previous studies and the current study, we found that the loss of ANXA7 is associated with the worst forms of prostate cancer." (PMID 37240163, 2023). "ANXA7 inhibits tumor growth and cell proliferation, and its loss of expression has been correlated with late-stage prostate cancer." (PMID 36247003, 2022). "Tumor suppressor function of the calcium/phospholipid-binding Annexin-A7 (ANXA7) has been shown in Anxa7-deficient mice and validated in human cancers, particularly for prostate cancer." (PMID 30321230, 2018). "miR-155 is an important immunomodulatory miRNA implicated in the induction of breast, lung, liver, and prostate cancer, where it promoted cell proliferation, as well as targeted and significantly downregulated annexin A7." (PMID 29462943, 2018). "We also showed that ANXA7 protected normal prostate cells and induced RB-associated cytotoxicity in prostate cancer cells in vitro." (PMID 24864229, 2014). "Loss of heterozygosity at the ANXA7-harboring 10q-locus and a particular loss of ANXA7 expression in the hormone-refractory prostate tumors provided evidence for the hormone-related tumor suppressor role of ANXA7 in prostate cancer." (PMID 24864229, 2014). "Multiple roles of hnRNPs complex on Anxa7 tumor suppressor protein have been demonstrated as potential inducer of Anxa7 alternative splice variants in prostate cancer." (PMID 24550987, 2014). "In prostate cancer, decreased expression of annexin A4 has been shown to correlate with worsen pathological stage, and loss of annexin A7 has been associated with metastatic and local recurrences of hormone refractory prostate cancer." (PMID 18071363, 2008). "Our previous study indicated that ANXA7 is linked to the RB/p21 axis and protects normal prostate cells and induces distinct patterns of RB-associated cytotoxicity in androgen-sensitive and -resistant prostate cancer cells." (PMID 39684934, 2024). "Recent studies have linked ANXA7 to hormone transport and prostate cancer." (PMID 37240163, 2023). "Previous studies related to ANXA7 focused more on carcinoma, including hepatocarcinoma, prostate carcinoma and breast cancer." (PMID 38149096, 2023). "To detect the possible mTOR involvement in the tumor suppressor effects of ANXA7 in prostate cancer cells, we juxtaposed the microarray-derived mTOR gene expression and apoptotic rates based on PS exposure and cell membrane permeabilization (ANXAV-PE)." (PMID 37240163, 2023). "Using DU145 as a prostate cancer (PrCa) model where wt-ANXA7 and DN-ANXA7J displayed the most contrasting effects, we found that the annexin properties of wt-ANXA7/DN-ANXA7J can be further implicated in the cell survival modulation." (PMID 37240163, 2023). "Adenovirus vectors containing either the wild-type ANXA7 (wt-ANXA7) gene or the dominant-negative mutant ANXA7J (DN-ANXA7J) were transfected into the DU145 prostate cancer cell line and tested for their growth inhibition." (PMID 37240163, 2023). "The genes are ordered according to our list of priorities for validating their involvement in the wt-ANXA7-induced effects on prostate cancer progression." (PMID 37240163, 2023). "In this study, we described the role of ANXA7 in cellular fusion and how it is relevant to the trafficking and eventually the link with prostate cancer." (PMID 37240163, 2023). "The number of apoptotic DU145 prostate cancer cells increased with the addition of wt-ANXA7 from 5% to 39% with DN-ANXA7J." (PMID 37240163, 2023). "ANXA7 is known to interact with the androgen receptor (AR), a key regulator of prostate cancer growth." (PMID 37240163, 2023). "Our studies with prostate cancer cells imply that the overexpression of ANXA7 increases the IP3 receptor expression, and the dominant-negative ANXA7J mutant downregulates the IP3 receptor expression." (PMID 37240163, 2023).
prostate carcinoma (continued). "Previous studies have reported that ANXA7 was related with cell survival in prostate cancer, glioma and pancreatic cancer." (PMID 37620352, 2023). "Considering the possibility of ANXA7 involvement in arachidonate-regulated phospholipid aggregation and exocytosis, we explored the effects of wt-ANXA7 or DN-ANXA7 on the lipid-relevant gene expression in human prostate cancer cells." (PMID 37240163, 2023). "ANXA7, identified by PermFIT-DNN and PermFIT-RF, is reported to be associated with prostate cancer and breast cancer, and its encoded protein has an impact on prostate cancer and breast cancer." (PMID 34021151, 2021). "In summary, we confirmed a prognostic significance of ANXA7 in prostate cancer and concluded that ANXA7 is an independent predictor of poor overall survival with a p-value of 0.01." (PMID 30321230, 2018). "This study thus provides evidence for the importance of various ANXA7 expression levels in the determination of tumor progression and survival rates in prostate cancer patients." (PMID 30321230, 2018). "ANXA7 is a tumor suppressor gene, and higher expression will be increased the overall survival of prostate cancer patients." (PMID 30321230, 2018). "We also analyzed the expression of ANXA7 and survival of prostate cancer patients with respect to CD-10 expression." (PMID 30321230, 2018). "Altogether, these results point towards a significant prognostic impact of ANXA7 in prostate cancer and warrant further investigation." (PMID 30321230, 2018). "Next, we analyzed the correlation between ANXA7 level and survival rates in terms of neoadjuvant therapy applied to the prostate cancer patients." (PMID 30321230, 2018). "Herein, we have identified the prognostic impact of ANXA7 in a prostate cancer using a tissue microarray containing 637 different specimens." (PMID 30321230, 2018). "The human ANXA7 (genetic position at 10q21) has displayed a tumor suppressor role in multiple in vivo and in vitro studies involving prostate cancer samples." (PMID 30321230, 2018). "Annexins A1, A2, A4, and A6 are downregulated in prostate cancer, and annexin A7 is a candidate tumour suppressor gene, inhibiting prostate cell migration." (PMID 29462943, 2018). "Our current findings suggest that the wt-ANXA7 was able to inhibit the proliferation of prostate cancer cells; enhance the sensitized prostate cancer cells, leading to cell death; and identify signaling pathways that were responsible for the tumor suppressor function." (PMID 37240163, 2023). "However, in prostate cancer cells, ANXA7 is often downregulated, leading to increased AR signaling and cancer cell proliferation." (PMID 37240163, 2023). "Indeed, ANXA7 is a tumor suppressor gene at position 10q21, and the copy number alteration (CNA) is associated with a worse prostate cancer prognosis." (PMID 37240163, 2023). "Since ANXA7 can potently suppress the proliferation of DU145 prostate cancer cells, we extended the study to test whether transiently transfected wt-ANXA7 promotes the apoptotic state of DU145 cancer cells." (PMID 37240163, 2023). "Specific alterations in phospholipid turnover and arachidonate cascade under wt-ANXA7 could involve the autophagy-relevant control over cell survival with different end results in prostate cancer cells compared with DN-ANXA7J." (PMID 37240163, 2023). "Therefore, we tested prostate cancer cells for the effect of the wild-type and the dominant-negative triple mutant ANXA7 on the cytotoxicity assay." (PMID 37240163, 2023). "ANXA7 may act as an oncogene in gastric cancer, hepatocellular carcinoma, nasopharyngeal carcinoma and breast cancer; or as an oncosuppressor in melanoma, prostate cancer, and glioblastoma." (PMID 36247003, 2022).
prostate carcinoma (continued). "At the same time, annexin A7 has been proposed as a putative tumor suppressor gene in prostate cancer while, a recent study revealed that annexin A7 expression was downregulated in late-stage gastric cancer and is negatively correlated with the differentiation grade and apoptosis." (PMID 31581454, 2019). "Besides, our ANXA7+/- mice study has demonstrated a cancer-prone phenotype, developing a spectrum of tumors including prostate cancer." (PMID 30321230, 2018). "While low levels of ANXA7 are associated with aggressive types of cancer, the clinical impact of ANXA7 in prostate cancer remains unclear." (PMID 30321230, 2018). "Four types of ANXA7 expression can be discriminated in the prostate cancer specimens." (PMID 30321230, 2018). "Our present high throughput TMA study extended our understanding of the role of ANXA7 towards prostate cancer patients’ survival and established its bimodal function as a tumor apoptotic marker (with optimal level) and tumor proliferative marker (with extremely low or high concentrations)." (PMID 30321230, 2018). "Therefore, PLD1 downregulation by wt-ANXA7 could mediate its cell elimination effects (especially in prostate cancer)." (PMID 37240163, 2023). "Similarly, in prostate cancer, ANXA7 may play a role in the transport of androgens, which are essential for prostate cancer growth." (PMID 37240163, 2023). "Furthermore, the relevance of ANXA7 to prostate cancer was also emphasized in this study." (PMID 37240163, 2023). "ANXA7 might act as a tumor suppresser gene in glioblastoma multiforme, glioblastoma, melanoma, prostate cancer and breast cancer; ANXA7 might specifically function as a tumor promoter gene in HCC, gastric cancer, nasopharyngeal carcinoma, and colorectal cancer." (PMID 34716295, 2021). "The functional role of annexin A7 in different cancers is still controversial as some of the data indicate that it functions as a tumor-suppressor gene in prostate cancer, melanoma, however might act as tumor promoter in gastric cancer, liver and breast cancer." (PMID 31581454, 2019). "Therefore, the higher expression of ANXA7 should be beneficial for the prostate cancer patients." (PMID 30321230, 2018). "Our finding in this current study demonstrated that when syndecan-1 is positive, a higher expression of ANXA7 further decreases survival rate, highlighting the importance of ANXA7 as an important biomarker along with syndecan-1 for the prediction of survival rates in prostate cancer patients." (PMID 30321230, 2018). "The results suggest that glutamic and aspartic acid are involved in calcium and phospholipid binding as determinants of ANXA7 action on IP3 receptor expression and prostate cancer cell survival acting via the PI3K/mTOR pathway." (PMID 37240163, 2023). "In the DU145 prostate cancer cell line, IP3 receptor expression was significantly elevated after exposure to wt-ANXA7 and decreased with DN-ANXA7J." (PMID 37240163, 2023). "Consistently, in this study, wt-ANXA7 and DN-ANXA7J distinctly interfered with apoptosis as well as arachidonate lipoxygenation in prostate cancer cells." (PMID 37240163, 2023).
prostate carcinoma (continued). "The results suggest that the glutamic and aspartic acid residues involved in calcium and phospholipid binding serve as the determinants of ANXA7 action on IP3 receptor expression and prostate cancer cell survival via the PI3K/mTOR pathway." (PMID 37240163, 2023). "A different study has indicated a physical interaction between RKIP and Annexin A7 (ANXA7), a suppressor of tumorigenesis and metastasis in prostate cancer." (PMID 30149591, 2018). "Furthermore, in our multi-tumor tissue microarray study, we found that ANXA7 protein expression was repetitively decreased in several different tumor tissues, demonstrating a typical tumor suppressor gene pattern, with a specific reduction in androgen-resistant prostate cancers." (PMID 30321230, 2018). "However, our current tissue microarray studies indicated that the very high expression (level 3) is not helpful for the survival of prostate cancer patients; indicating bimodal functions of ANXA7 for prostate cancer." (PMID 30321230, 2018).
breast carcinoma (15 papers, 2008 to 2024). "Human ANXA7 has been mapped to tumor susceptibility locus 10q21 with 35% loss of heterozygosity in prostate and breast cancer indicating its possible tumor suppressive function." (PMID 24963320, 2014). "ANXA7 has also been shown to play a role in the transport of estradiol, a key estrogen hormone, in breast cancer cells." (PMID 37240163, 2023). "In Her2-negative breast cancer, ANXA7 expression correlated with metastasis and low survival rate, and serves as a diagnostic and prognostic biomarker for these patients." (PMID 36247003, 2022). "The levels of ANXA7 expression in liver cancer, breast cancer nasopharyngeal cancer, gastric cancer, colorectal cancer, and cervical squamous cell carcinomas are increasing." (PMID 33397392, 2021). "The levels of ANXA7 expression in liver cancer, gastric cancer, nasopharyngeal cancer, colorectal cancer, cervical squamous cell carcinomas and breast cancer were increased." (PMID 32526706, 2020). "We show that both ANXA5 and ANXA7 are required for repair in breast cancer cells in addition to our previous results implicating ANXA4, ANXA6 and ANXA213, indicating that a network of annexins are participating in the plasma membrane repair response." (PMID 31040365, 2019). "Here, using invasive breast cancer cells we show that the Ca2+ - and phospholipid-binding protein annexin A7 is part of the plasma membrane repair response by enabling assembly of the endosomal sorting complex required for transport (ESCRT) III." (PMID 31040365, 2019). "ANXA7 might specifically function as a tumour promoter candidate in liver cancer, breast cancer, nasopharyngeal carcinoma, gastric cancer, and colorectal cancer." (PMID 33397392, 2021). "Annexin A7 is a tumor suppressor in human prostate and breast cancers." (PMID 24392146, 2014). "This is the first time indicating the effect of propolis on ANXA7 in breast cancer cells, which might be a new target of propolis on antitumor study and treatment." (PMID 24963320, 2014). "Annexin A7 has been shown to be a tumor suppressor in hormone-relevant prostate and breast cancers." (PMID 24188284, 2013). "Thus, our work here identifies a novel role of ANXA7 in cell survival, which may open for novel approaches to target aggressive breast cancer cells by inhibiting plasma membrane repair." (PMID 31040365, 2019). "In addition, altered expression of Annexin A7 could affect the tumor stage and survival in hormone-refractory human prostate and breast cancers." (PMID 24188284, 2013). "In breast cancer, studies have proven that ANXA2, ANXA4, ANXA5, ANXA6, and ANXA7 are required for repair in breast cancer cells, indicating that a network of annexins participate in the plasma membrane repair response." (PMID 34484309, 2021). "With the ubiquity of ANXA7 expression and plasma membrane injury, the role of ANXA7 in mediating plasma membrane repair by recruiting ESCRT III machinery may be broadly relevant, but heightened further in invasive breast cancer cells." (PMID 31040365, 2019).